NF1 (neurofibromin 1)
Diseases named in the same sentence as NF1 in open-access papers (continued):
Sharing a sentence is not in itself a finding about the gene and the disease.
tumor (continued). "Here, we describe the preclinical efforts that led to the identification of MEK inhibitors as promising therapeutics for the treatment of NF1-related neoplasia and possible reasons they lack single agent efficacy in the treatment of MPNSTs." (PMID 32353955, 2020). "Among four patients, one experienced relapse; the tumor harbored a SNV in NF1 (Arg1362*) and ROS1-GOPC fusion." (PMID 32493317, 2020). "We previously demonstrated that YAP/TAZ were activated in both human and mouse NF1-null cutaneous neurofibromas, a tumor driven by dysregulated RAS/MAPK signaling." (PMID 32960816, 2020). "Genes positively selected under both conditions were enriched for known tumor suppressors, such as NF1 and NF2, as expected." (PMID 32413516, 2020). "The internal tumour load was determined by volumetry of whole-body magnetic resonance imaging (MRI) in 20 children and adolescents with NF1 microdeletions." (PMID 32533297, 2020). "Typical GBM alterations, such as IDH mutation, NF1 inactivation, and CDK4-MARCH9 locus amplification, characterize tumor-associated immunosuppression." (PMID 33228738, 2020). "Recent evidence indicates that NF1 is a transcriptional co-repressor of Estrogen Receptor (ER) alpha in mammary epithelial cells, thus revealing an additional GAP-independent tumor-suppressive function linked to its nuclear localization." (PMID 33096593, 2020). "Studies on pathological splicing mutations support the importance for DAZAP1 in RNA splicing of several key tumor suppressors, such as NF1, BRCA1 and ATM38." (PMID 32308763, 2020). "We found that two of the top LVs with lower expression in cNF but higher expression in other tumor types, LV 384 and LV 624, had ties to known Schwann cells and NF1 tumor biology, as well as presence of immune cells in the tumor microenvironment." (PMID 32098059, 2020). "NF1 loss is also seen in the majority of sporadic MPNST, suggesting NF1 is an important tumor suppressor in all MPNSTs." (PMID 32089640, 2020). "LOH or AST mutation was detected in at least one tumor with PALB2, ATM, RAD51D, BARD1, BRIP1, RAD51C, or NF1 germline mutation." (PMID 32566746, 2020). "Further investigation is needed to definitively address the contribution of collagen to NF1-related tumour development." (PMID 32439933, 2020). "The presence of multiple tumors in affected patients and the identification of somatic mutations within the NF1 gene in sporadic tumors independently of NF1 disease has led to NF1 being designated as a tumor suppressor gene." (PMID 33121128, 2020). "A wide range of animal models has been developed to study the intracellular signalling pathways as well as extracellular signals that regulate tumour development in NF1." (PMID 32439933, 2020). "Some NF1 patients experience a subjective increase of NF1-related clinical symptoms and tumor growth during pregnancy." (PMID 32343738, 2020). "Case 3: The donor was a 72-year-old man with NF1 with an original tumor developed in the right shoulder, and several rounds of surgery and radiation therapy had been performed in another hospital." (PMID 32099531, 2020). "The 2 other cases had NF1 and were operated on in the early period of our retrospective analysis due to larger tumours." (PMID 32506255, 2020).
tumor (continued). "The study showed a dramatically inhibition of the RAS pathway and tumor development, laying the foundations for a possible future gene therapy for NF1." (PMID 32326947, 2020). "There was a detectable reduction in copy ratio (CR) near the NF1 locus (CR of blood = 1, CR of tumor = 0.5)." (PMID 32561749, 2020). "In the current study, samples were taken from three distinct areas within a single tumor from a patient with an NF1-MPNST." (PMID 32369930, 2020). "KRAS was suggested as a biomarker for treatment with AZD6244 (Selumetinib), which is a MEK1 inhibitor, while another phase II clinical study identified that NF1 was also indicative of tumor response to AZD6244." (PMID 32604779, 2020). "In NF1-MET tumors, doxorubicin treatment caused a significant decrease in tumor growth (p < 0.0005); however, doxorubicin treatment was inferior to capmatinib or trametinib." (PMID 32245042, 2020). "The RAS/MAPK and PI3/AKT signaling pathways are enabled due to RET proto-oncogene activation or NF1 tumor suppressor inactivation, resulting in tumor formation." (PMID 33081307, 2020). "Loss of NF1 leads to activation of the MEK-ERK and PI3K-Alt-mTOR pathways, and for this reason, NF1 can be considered a tumor suppressor." (PMID 33348922, 2020). "After 21 days of capmatinib treatment, significant tumor death was observed in the NF1-MET tumors, with only a small layer of viable cells present at the edge of the tumors." (PMID 32245042, 2020). "In comparison to NF1-shRNA vector-transduced cells, clear demarcation between tumor and normal region was observed in NF1-LRD-expressing tumor, whereas invasive cells were notably visible in NF1-shRNA vector-transduced tumors (red arrows)." (PMID 30967630, 2019). "Both STX3451 and STX2895 provide new approaches for inducing cell death and lowering tumour burden in NF2 as well as in NF1, which both have limited treatment options." (PMID 31730023, 2019). "SPRED1 is a tumor suppressor that acts by transporting NF1 to the plasma membrane where it inhibits RAS-GTP signaling." (PMID 31320640, 2019). "T-test for independent samples comparing the two groups of patients with tumors taken together to NF1 non-tumor group, confirmed all the significant differences revealed by one-way ANOVA except for Digit Span test." (PMID 31717965, 2019). "NF1 status and increasing tumor size remain the most important predictors of OS in MPNSTs in our population." (PMID 30735009, 2019). "B-Raf is the effector of Ras, the most upstream activator of the MAPK pathways downstream from growth factor receptors, whose inhibitor, NF1, is a tumor suppressor that is also inactivated in a large variety of cancers." (PMID 31258848, 2019). "We further demonstrate that pathogenic mutations within this domain abolish its invasion suppression function, suggesting a role for the NF1-LRD against tumor metastasis and invasion." (PMID 30967630, 2019). "To rule out the effect of cell culture, we additionally assessed the expression of SOX2, Vimentin and CD44 protein in NF1-LRD-expressing tumor." (PMID 30967630, 2019). "Of the known effectors of NF1-loss associated signaling, p38, STAT3, AKT, mTOR, and TGF-β have been previously linked to heightened tumor aggressiveness." (PMID 30967630, 2019). "Although the bioavailability of STX3451 and STX2895 has not been examined in an animal model, the in-vitro effects of these molecules on NF1 cell lines derived from both benign and malignant human tumours are particularly promising." (PMID 31730023, 2019). "Accordingly, we observed that Nf1 overexpression in Kras‐mutant LUAD is associated with suppressed LUAD cell proliferation and xenograft tumor growth." (PMID 31036704, 2019).
tumor (continued). "Within the Ras/RTK pathway, epidermal growth factor receptor (EGFR, 30–50% of tumours) and phosphatase and tensin homolog (PTEN, 30%) are the most commonly mutated in GBM, although mutations in NF1 and RAS have also been documented." (PMID 31505839, 2019). "As a tumor suppressive role has predominantly been suggested for both NF1 and RASA1, we continued to investigate both their function in CRC." (PMID 30858928, 2019). "Tumour growth in NF2 cells is affected by different inhibitors from those affecting NF1 growth pathways: specifically, NF2 cells are affected by merlin-downstream pathway inhibitors." (PMID 31730023, 2019). "Our previous studies concluded that the agents’ effects on the growth of and induction of apoptosis in human NF1 tumour cells were both through NF1-specific pathways and through significant effects on both the actin-based and myosin-based cytoskeleton." (PMID 31730023, 2019). "Consistent with the findings collected in mice, we did not observe any significant difference in the expression of the two NF1 isoforms in relation to tumor formation or vascular disease." (PMID 31730495, 2019). "Inactivation of the NF1 tumor suppressor in MPNST results in upregulation of mTOR (mammalian target of rapamycin) signaling and angiogenesis, which contributes to disease progression." (PMID 31427883, 2019). "In the context of NF1-associated tumors, this seems to be NF1 loss, while IDH mutations and histone H3 mutations (particularly G34) frequently coexist with ATRX loss in other tumor subsets." (PMID 31462295, 2019). "To investigate the molecular mechanism that underlies increased tumor growth and EGF-independent survival upon loss of NF1 expression, we analyzed the activity of the RAS-MAPK signaling pathway." (PMID 30858928, 2019). "For what concerns NF1 + CT, any relevant differences have been found comparing children with tumor in the brainstem or in the hypothalamus vs. tumors in other areas." (PMID 31717965, 2019). "A second tumor (patient #1) was found to have three disease associated variants: BRAF c.1799 T > A p.(V600E), NF1 c.7079_7082delTTAT p.(F2360Wfs*35), and TSC1 c.2074C > T p.(R692*)." (PMID 31046843, 2019). "Beyond its involvement in NF1, the NF1 gene behaves as a tumor suppressor in a number of sporadic malignancies." (PMID 31739524, 2019). "We also observed significant increases in tumor burden 21 weeks after infection with sgRNAs against Nf1 as compared to sgTom." (PMID 31036704, 2019). "Our results showed that NF1-knockdown tumor had higher percentage of vimentin and CD44-positive cells." (PMID 30967630, 2019). "As expected, overexpression of WT Nf1 in KPΔNF1 cells downregulates Fak1, downregulates its target genes Psat1, Areg, and Peg10, retards tumor growth, and rescues cytotoxicity induced by CB‐839 or AOA." (PMID 31036704, 2019). "Little is known about the role of ncRNAs—in particular, miRNAs and lncRNAs mainly involved in cancer—on benign and malignant tumor development in relation to NF1." (PMID 31694342, 2019). "High proportions of NF1-positive tumor cells were also found, but the IR was almost moderate to mild for this protein." (PMID 31803613, 2019). "Patients with NF1 MPNST were younger (median age 28 years) compared with sporadic MPNST (median age 61 years), consistent with NF1 being a tumor suppressor." (PMID 31427883, 2019). "We observed that a functionally important gene such as NF1 (a gene which serves as a tumour suppressor and acts in fibroblast proliferation) was both hypermethylated and downregulated." (PMID 29426343, 2018). "NF1 deficient GBM frequently shows a mesenchymal gene expression signature, suggesting a relationship between NF1 status and the tumor microenvironment." (PMID 29643433, 2018).
tumor (continued). "On the one hand, our model stipulates that an Nf1+/− microenvironment accelerates the formation of benign tumors." (PMID 30479396, 2018). "Altogether, these human clinical data align well with our conclusion derived from the DMBA/TPA-induced tumor study, in which an Nf1+/− microenvironment played an antagonistic role throughout the stepwise cancer progression." (PMID 30479396, 2018). "Treatments are yet based on symptomatic surgical interventions of the NF1 tumours and on improving the NF1 specific learning disabilities by drugs." (PMID 29670214, 2018). "In NF1, several tumor types have been shown to have inactivation of the wild-type NF1 allele, supporting the notion that NF1 is a bona fide tumor suppressor gene." (PMID 29643433, 2018). "We found that patients with an NF1 shallow deletion had significantly higher tumor grade, stage, and size." (PMID 30182054, 2018). "A germline perturbation affecting NF1 or NF2 can be considered a tumor initiation event, explaining why this germline disorder guarantees the formation of multiple benign nerve sheath tumors over one’s lifetime." (PMID 29616301, 2018). "The analysis also revealed NF1 shallow deletions correlate with higher tumor grade, tumor size, and the aggressive, basal subtype." (PMID 30182054, 2018). "NF1 mutations co-occurred with BRAF and RAS gene mutations in some tumours, but also frequently occurred alone." (PMID 29559732, 2018). "Estrogen-dependence was verified by estrogen-ablation in Nf1 rats where rapid tumor regression was observed." (PMID 30182054, 2018). "If many asymptomatic OPGs are actually areas of immature myelin instead of true neoplasms, it will change our understanding of NF1 pathology." (PMID 29685181, 2018). "Typical examples included known or putative tumor suppressors, such as NF1, DICER1, PML, PDS5A, MAP3K7, and PPP2R5A, in which SF3B1 mutation resulted in usage of alternative 3′ splice sites." (PMID 30194306, 2018). "This association between NF1 loss and the mesenchymal gene expression pattern suggests a direct role for GBM NF1 status influencing the tumor microenvironment." (PMID 29643433, 2018). "The gene community containing the tumor suppressors NF1 and SPRED1 illustrates this phenomenon (Fig EV5C)." (PMID 30573688, 2018). "The germline mutations underlying NF1/NF2 and Li–Fraumeni syndrome represent pathways that both need to be disrupted for a malignant tumor to form." (PMID 29616301, 2018). "Tumor cells with Ras/NF1 dysregulation have been shown to be sensitive to disruption of cellular reactive oxygen species management and proteotoxicity management mechanisms." (PMID 29662612, 2018). "Mitogen-activated protein kinase kinase (MAPK2/MEK), an integral signalling component of the Ras pathway, is a compelling target in many NF1-related tumours." (PMID 29695767, 2018). "This approach, as well as the previously designed cNF number measurement protocol, was employed to prospectively monitor tumor number and size in a cohort of 22 adult patients with NF1 over an 8-year period." (PMID 29415745, 2018). "In summary, mutations in the MAPK pathway, specifically NF1, were associated with both LRR and DM, suggesting that alterations in MAPK signaling are associated with a more aggressive tumor phenotype." (PMID 30345349, 2018). "In the non-NF-1 group, the tumor involved the hypothalamus in 8 patients (61%), optic chiasma in 8 (61%), optic tract in 3 (23%), and optic nerve in 3 (23%)." (PMID 30619059, 2018). "There are few case reports detailing a link between increasing tumor size in pregnant patients with NF1 likely due to the increase in hormones." (PMID 30116681, 2018). "Here the authors use mouse models to show that an NF1 heterozygous microenvironment accelerates the formation of benign tumours but impairs progression to malignancy." (PMID 30479396, 2018).
tumor (continued). "Correlation of our in vitro finding with TCGA data suggests an in vivo association between NF1 status and tumor production of CHI3L1 and ENG, supporting an association between NF1 and mesenchymal identity in human GBM samples." (PMID 29643433, 2018). "Our findings suggest that in adult patients with NF-1 who have PNF involving PH most of the times the tumor is unresectable on imaging." (PMID 29849532, 2018). "Nf1 rats (including in-frame and premature stop indels) were aged to determine the effects of Nf1 alterations on tumor development." (PMID 30182054, 2018). "Mutations and structural alterations of the NF1 tumor suppressor gene are common in GBM, but the significance of these genetic alterations for tumor behavior is not fully understood." (PMID 29643433, 2018). "A phase 1 study of children with NF1 treated with the MEK inhibitor Selumetinib revealed promising reduction of the plexiform neurofibrosarcoma tumour mass in 17 of 24 patients." (PMID 29670214, 2018). "The fact that nearly all patients with NF1/NF2 develop one or more benign tumors can be understood by acknowledging that in these disorders a germline tumor initiation event is involved." (PMID 29616301, 2018). "• Early diagnosis of abdominal manifestations of NF-1 based on imaging patterns is necessary for appropriate treatment to avoid serious organic complications related to tumour mass." (PMID 30187267, 2018). "One such alteration is the loss of neurofibromin 1 (NF1), an important tumor suppressor that regulates the activity of RAS GTPases." (PMID 28166733, 2017). "Cluster 2 contains tumours with mutations in RET, TMEM127, MAX, NF1 and HRAS and is characterized by aberrant activation of kinase signalling pathways." (PMID 28327598, 2017). "Although analyzed separately, these additional samples corroboratedthe mutations above and highlighted additional recurrent mutations in theBRCA2, MLL3, APC,NF1, and ELF3 tumor-suppressor genes." (PMID 28297679, 2017). "Disease stabilization and small reductions in tumor size in addition to the partial responses were seen in patients with NF1 and sporadic MPNST and appeared similar in magnitude." (PMID 29138631, 2017). "Another tumour suppressor gene located within the NF1 microdeletion region is ATAD5 (ATPase family AAA domain–containing protein 5)." (PMID 28213670, 2017). "Recent studies have shown that NF1 is a tumor suppressor that plays a critical role in many cancers." (PMID 29137312, 2017). "Sarcoma arising from the peripheral nerve sheath is readily diagnosed as MPNST if the tumor clearly has nerve elements or arises in the context of NF1." (PMID 28592921, 2017). "Genome-wide microarray analysis of 36 primary OSC identified homozygous NF1 deletions in two tumours." (PMID 28637487, 2017). "Immunohistochemical staining of 160 matched GC tumor and adjacent normal tissue samples showed that 58.1% (93/160) of GC samples were NF1-positive as compared to 94.4% (151/160) of normal tissue samples (χ2=58.05, P <0.001)." (PMID 29137312, 2017).